MYC (MYC proto-oncogene, bHLH transcription factor)
Diseases named in the same sentence as MYC in open-access papers (continued):
Sharing a sentence is not in itself a finding about the gene and the disease.
cancer (continued). "Mutations in MYC genes have been found in many tumors and C-MYC is upregulated and acts as an oncogene in more than 50% of human cancers." (PMID 35205716, 2022). "IFITM1 affects the levels of pAkt, pSTAT3, SOX2, MYC and p-β-catenin, which are linked to cancer stem cell regulation." (PMID 36466909, 2022). "In bulk tissues, variation in total mRNA amount—that is, the sum of detectable mRNA transcripts across all genes per cell—has been indirectly linked to cancer progression and de-differentiation as a result of MYC activation or aneuploidy." (PMID 35697807, 2022). "Replication stress and genomic instability are part of the cancer‐associated phenotypes and are found in MYC‐driven cancer." (PMID 36214609, 2022). "The findings from cancer hallmarks analysis illustrated that the LMR-lncRNA signature in the high-risk group triggered MYC targets, glycolysis, hypoxia, and PI3K/AKT/mTOR signaling." (PMID 35422758, 2022). "Dysregulation of the MYC proto-oncogenes (amplification or chromosomal translocation) that encode for transcription factors frequently present in human cancers." (PMID 35448150, 2022). "The loss of FBXW7γ in cancer cells leads to MYC stabilization which likely enhances rRNA production." (PMID 35159381, 2022). "Most cancers have complex genetic mutational patterns where multiple growth-promoting proteins, for instance, MYC and β-catenin, cooperate to promote survival and proliferation." (PMID 35269436, 2022). "The most frequently upregulated hallmark gene sets in cancers were MYC targets v1, E2F targets, and MYC targets v2, which were upregulated in 17, 17, and 16 site-specific cancers, respectively." (PMID 34203763, 2021). "MYC is located in the 8q24 band, a hotspot region for chromosomal rearrangements and SNPs associated with different types of cancer and a frequent site of viral integration." (PMID 34885058, 2021). "Collectively, this emphasizes a broad, multilayered role of IGF2BP1 in promoting key cancer hallmark pathways like MYC/N- and E2F-driven gene expression." (PMID 33829040, 2021). "While c-MYC protein is important for normal cellular function in many cell types, when mutations eliminate the reliance of c-MYC activation on growth factor signaling, this oncogene helps drive cancer initiation and progression." (PMID 33513764, 2021). "A primary downstream target of BRD4 is MYC—a member of the myc family of transcription factors encoded by the proto-oncogene, which is frequently deregulated in cancer." (PMID 34681760, 2021). "The c-MYC dysregulation in cancers is mainly induced through gene amplification, chromosome translocation, super-enhancer activation, and loss of upstream repressors to stabilize the c-MYC protein expression." (PMID 34887764, 2021). "This makes MYC proteins not only significant targets for novel therapeutic approaches in cancer, but relevant biomarkers for early risk-stratification of patients." (PMID 34689785, 2021). "MYC activation is associated with many features of cancer, including protein synthesis, proliferation and altered cellular pathways." (PMID 34783629, 2021). "Successful concepts for precision oncology require strong drivers of cancer subtypes as biomarkers, that are associated with different drug sensitivity phenotypes, like MYC." (PMID 34637026, 2021).
cancer (continued). "Among them, MYC mediated transcriptional amplification through super-enhancers is an essential hallmark of cancer." (PMID 34079579, 2021). "MYC is one of the most extensively studied cancer-causing genes, having been linked to the development, maintenance, and advancement of a variety of cancers." (PMID 34853590, 2021). "This is based on the strong biology and specific phenotypes associated with MYC, the differential drug sensitivity of cancers with deregulated MYC, and the emerging ability to image MYC non-invasively." (PMID 34637026, 2021). "Lung tumors driven by strong cancer drivers (mutant EGFR and Kras) harbored few mutations in cancer-related genes, whereas tumors driven by MYC, a weak driver in the murine lung, harbored recurrent clonal oncogenic KRAS mutations." (PMID 34200786, 2021). "Given its pivotal role as a driver in cancer progression and maintenance, as well as its association with drug resistance, c-MYC has become an ideal target for cancer therapy." (PMID 33718147, 2021). "Supporting previous findings that super-enhancers play important roles in cell identity and cancer hallmarks, we observed super-enhancers associated with several known GC oncogenes, such as MYC, KLF5, and EGFR." (PMID 34635154, 2021). "Mutations on the phosphorylation sites that stabilize MYC have been identified in human cancers, thus highlighting the relevance of S62 and T58 phosphorylation as regulators of MYC tumorigenic activity." (PMID 33718197, 2021). "c-MYC, involved in cell proliferation, apoptosis, and tumorigenesis, is associated with poor prognosis, progression, and invasion in human cancers." (PMID 35432798, 2021). "YAP/TAZ activation can be influenced by heterogenous cancer-cell intrinsic features (i.e., underlying genetic lesions) and mechanical cues, and is interconnected with mitogenic signals (i.e., MYC) and WNT/β-catenin signaling." (PMID 33879786, 2021). "Although the role of MYC as a driver in many human cancers is clear, the underlying molecular mechanisms still need to be elucidated and the possibility of selective targeted therapies remains in doubt." (PMID 33801599, 2021). "The recent discovery that super-enhancers in cancer cells are associated with major oncogenes, such as the MYC gene, has identified the BET protein family as a valuable drug target in cancer and fostered the development of several inhibitors." (PMID 34208195, 2021). "MYC, cell cycle-related pathways, and cancer stemness are associated with the SL subtype, and EMT and TGF-β pathway activation is implicated in the MSL subtype." (PMID 34771636, 2021). "Here, we present evidence that cancer cells carrying oncogenic MYC are susceptible to growth inhibition by treatment with the HDAC inhibitor, SAHA." (PMID 34262032, 2021). "DDX6 expression is associated with the IRES-dependent c-MYC translation to regulate cancer cell growth and differentiation." (PMID 34887764, 2021). "We also observed that the chromosomal region 8q22.3–8q24, is amplified in multiple tumors, and includes RRM2B, MYC along with several other cancer-associated genes." (PMID 33868369, 2021). "Numerous genetic polymorphisms associated with cancer risk are located within the non-coding regions surrounding MYC, which has led to characterising these regions as regulatory elements influencing MYC expression." (PMID 33499210, 2021). "The transcription factor MYC is the most frequently amplified gene in human cancer and is overexpressed because of mutations in an array of oncogenic signaling pathways." (PMID 34676047, 2021).
cancer (continued). "The MYC gene encodes for the transcription factor MYC, which is upregulated in 70% of all cancers and drives oncogenesis by altering cell proliferation, metabolism, and immune evasion." (PMID 33632214, 2021). "In contrast, sustained suprabasal expression of c-MYC induces proliferation, hyperplasia, papilloma formation, and angiogenesis, which are key processes associated with cancer progression." (PMID 34553848, 2021). "For example, abnormal amplification of MYC-encoding MYC proteins, which are key regulators of cell proliferation, increasingly promotes proliferation of the cancer cells." (PMID 33926508, 2021). "For example, the amplification of the oncogene MYC was significantly associated with elevated Glycolysis score in four independent cancer types (FDR < 0.05)." (PMID 34030708, 2021). "TERT and MYC, for example, have been linked to enhanced drug sensitivity of cancer cells to nelarabine, palbociclib, hydroxyurea, cytarabine, fluphenazine, fludarabine, carmustine, and other drugs." (PMID 34853590, 2021). "Nonetheless, MYC has been linked to many of the hallmarks of cancer and overexpression of MYC is directly transforming." (PMID 33760847, 2021). "The stemness-associated markers OCT4, NANOG, SOX2, KLF4 and c-MYC are expressed in numerous cancer types suggesting the presence of cancer stem cells (CSCs)." (PMID 34685477, 2021). "By showing that echinomycin simultaneously causing proteasomal degradation of MYC and HIF1α, our data provided a new approach to target these and potentially other oncogenic proteins for cancer therapy." (PMID 33572152, 2021). "The MYC oncogene family is dysregulated in > 50% of cancers, and is frequently associated with poor prognosis and unfavorable patient survival rates." (PMID 34295810, 2021). "The high- and low-risk groups had distinct performance in certain cancer-related processes, including DNA repair, epithelial mesenchymal transition, G2M checkpoint, and the MYC pathway." (PMID 34149792, 2021). "The MYC oncogene encodes the transcription factor, MYC, which triggers selective gene expression amplification to promote cancer cell growth and proliferation." (PMID 34295810, 2021). "Together, understanding metabolic reprogramming and its underlying genetic makeup, such as MYC activation, allows for a better understanding of the cancer cell phenotype and thus of the potential vulnerabilities of cancers from a metabolic standpoint." (PMID 34503295, 2021). "At the same time, MYC overexpression caused the reactivation of developmental pathways and the switch of the cancer cells towards a more aggressive stem-cell-like state." (PMID 34638453, 2021). "Due to the high amount of protein load in cancer cells and a protein biosynthesis machinery acting at the upper limit, cells with high MYC expression are associated with an increased unfolded protein response (UPR)." (PMID 34637026, 2021). "L-MYC has significantly lower transformation activity in cultured cells compared with other MYC members, and only a small number of human cancers have been associated with the aberrant expression of L-MYC." (PMID 34440750, 2021). "MYC signaling is implicated in the pathogenesis of most human cancers, and its deregulation is correlated with poor survival of patients." (PMID 34783629, 2021). "The upregulation of PCAT1, PRNCR1, PVT1, and MYC potentially confers the risk of cancer as their upregulation is strongly associated with prostate cancer." (PMID 32680982, 2020). "In cancer cells, increased consumption of glutamine has been linked to regulation of oncogenes like MYC." (PMID 33117715, 2020). "MYC expression is deregulated in a large proportion of cancers and its overexpression is linked with poor prognosis." (PMID 31973211, 2020). "Recent reports show that THZ1, a CDK7 inhibitor, suppresses SE-associated oncogenic transcription in MYC-deregulated cancer models." (PMID 33168807, 2020).
cancer (continued). "In cancer cells, MYC has been implicated as a key positive regulator of CAP-dependent mRNA translation, a process that was predicted to be downregulated upon Mettl3 ablation in embryonc skin." (PMID 32845239, 2020). "In many cancer types, the role of amplified MYC in mediating tumorigenesis has been linked to genes involved in ribosomal biogenesis, universally up-regulated transcription, proliferation, and reprogramming cells to a pluripotent state." (PMID 32681068, 2020). "MYC is dysregulated in more than half of human cancers and is usually in association with aggressive phenotype." (PMID 32690037, 2020). "Compared with MYC, PVT1 is less studied, but it is involved in critical processes in cancer cells, including DNA rearrangements, genetic instability, microRNA (miRNA) encoding, and also interacts with MYC itself." (PMID 32150871, 2020). "The excessive expression of MYC proteins causes aggressive behavior, associated with altered survival/proliferation and drug-resistance in cancer cells." (PMID 32085516, 2020). "MYC is an oncogene that participates in the tumourigenesis of most cancers and is associated with poor prognosis." (PMID 32316225, 2020). "Chromosome translocations, gene amplification, retroviral insertion or mutations of MYC gene are tumorigenic in mice and correlate with development of most human cancers." (PMID 33329574, 2020). "In NB and other cancers, targeting these transcriptional components leads to selective downregulation of superenhancer-associated genes, such as MYC or MYCN, that are characterized by high transcription levels and rapid turnover of RNA." (PMID 33016930, 2020). "CDC25A and B expression has been shown to be stimulated by the c-MYC oncogene and has been reported in many types of human cancers, possibly resulting from genome instability caused by the checkpoint-abrogating effect of their overexpression." (PMID 33385163, 2020). "Noticeably, p14ARF mRNA but not MILIP levels correlate with MYC gene expression in normal human tissues 62, whereas MILIP is upregulated and its expression is positively associated with the levels of MYC expression in human cancers." (PMID 33020477, 2020). "Increased levels of BCAT1, a target of c-MYC, has been previously associated with more aggressive cancers." (PMID 32907612, 2020). "In cancer cells, genetic and epigenetic dysregulation of MYC expression and the loss of checkpoint components unleash the ability of MYC to promote cell growth, eventually leading to malignant transformation." (PMID 32943735, 2020). "OCT4, NANOG, and c-MYC overexpression has been implicated in metastasis in many cancer types, including MM, in which cells expressing these markers have been shown to confer aggressive motility phenotypes, thus promoting invasiveness." (PMID 32019273, 2020). "MYC encodes a basic helix-loop-helix-leucine zipper (bHLH-LZ) transcription factor (TF) whose central oncogenic role in many human cancers makes it a highly desirable therapeutic target." (PMID 33628735, 2020). "Many studies have illustrated that PVT1 levels are higher in many cancers with an increased MYC expression than in normal tissues and are associated with a poor prognosis." (PMID 32992461, 2020). "Chromosome 8q24 has been implicated in many cancers and is known to contain regulatory elements for the tumor oncogene MYC located at 128,748,315-128,753,680 bp." (PMID 32894098, 2020). "Among them, c-Myc (MYC) is the gene most strongly associated with cancer, and it is the focus of this review." (PMID 33081056, 2020). "Activation of MYC causes abnormal cell proliferation, regression, and redifferentiation of cancer cells and susceptibility to aurora kinase inhibition in SCLC cells." (PMID 33299870, 2020).
cancer (continued). "Oncogenic levels of MYC regulates almost every aspect of cellular metabolism, a recently revisited hallmark of cancer development." (PMID 32651356, 2020). "There are frequent mutations of one or more MYC genes in various cancers, and the overexpression of ODC1 is regulated by MYC activation." (PMID 33292222, 2020). "Both PVT1 and the well-known protein-coding gene MYC are co-located on the 8q24 chromosomal region, known as the gene desert, which contains a large number of risk alleles that are implicated in cancer." (PMID 33076512, 2020). "Taken together with the in vivo data, these results support a role for altered MYC phosphorylation (loss of T58 and gain of S62 phosphorylation) in driving stem cell phenotypes, which likely contributes to tumorigenesis and cancer aggressiveness." (PMID 32895364, 2020). "The MYC gene is a major cancer driver, and deregulation of MYC expression is a hallmark of the majority of human tumors." (PMID 31944520, 2020). "Yes-associated protein (YAP) and c-MYC were selected to further confirm the specific contribution of O-GlcNAc-modified XIAP-dependent OGT degradation in cancer cells because both proteins are potent oncogenic factors and regulated by O-GlcNAc modification." (PMID 32994395, 2020). "The MYC gene is a major cancer driver, and elevated MYC protein levels are a hallmark of most human cancers." (PMID 31944520, 2020). "Activation of MYC caused abnormal cell proliferation, regression and redifferentiation of cancer cells, and susceptibility to Aurora kinase inhibition in SCLC cells." (PMID 32595734, 2020). "MYC is overexpressed in many different types of cancers, and its endogenous and pathogenic function is completely dependent on the interaction with its partner protein MAX, as only the heterodimer can bind DNA." (PMID 32225120, 2020). "The appearance of these highly ranked aberrant signaling nodes was plausible, since other autochthonous models have also reported upregulation of EMT-associated genes and MYC activation within the resulting Arid1a-null cancers." (PMID 32967217, 2020). "In parallel, subclone-specific mutated genes are highly enriched in cancer-related pathways, including MYC target, G2M checkpoints, and mitotic spindle, and immune-related pathways, such as interferon response, TNF-a signaling, and inflammatory response." (PMID 31937348, 2020). "High rate of ribosome biogenesis is strongly associated with poor prognosis across many cancer types, and it is commonly regulated by oncogenic signaling pathways including c-MYC, RAS-RAF-ERK, and PI3K–mTOR." (PMID 31285544, 2020). "MYC upregulation, caused by deregulated activity of MYC transcriptional network, enhances cancer proliferation and cellular drug resistance according to recent researches." (PMID 32096603, 2020). "PVT1 and PCAT1, located in the vicinity of the MYC oncogene, are encompassed by the 8q24.21 protein-coding gene desert–a region harboring many cancer risk variants, including CaP risk SNPs in men of African ancestry." (PMID 32059012, 2020). "The MYC oncogene encodes a transcription factor that is a central driver of cell-cycle progression in both normal settings and in cancer." (PMID 30902071, 2019). "PVT1 is a lncRNA with oncogenic function in multiple cancers and it maps on chromosome 8q24, a recognized cancer risk region that is shared with the well-known MYC oncogene." (PMID 31581735, 2019). "As elevated MYC is a universal hallmark of human cancer, a great deal of effort has been expended in attempts to identify, and ultimately manipulate, the molecular events that convert the proliferative MYC program into an apoptotic program." (PMID 30902071, 2019). "The MYC oncogene is deregulated in >50% of human cancers and its hyperactivation is associated with a poor prognosis and unfavorable patient survival." (PMID 31212916, 2019). "MYC expression has been linked to the regulation of a variety of cancer hallmark-related genes in tumors." (PMID 31824865, 2019).